RNY1 (RNA, Ro60-associated Y1)
Synonyms: hY1; Y1
Gene: Miscellaneous RNA gene on chromosome 7 (148,987,136 to 148,987,248, reverse strand). Ensembl gene ENSG00000201098.
Homologues: Orthologues: chimpanzee Y_RNA (100% identical), dog RNY1 (100% identical), macaque Y_RNA (100% identical), guinea pig Y_RNA (98% identical), pig Y_RNA (98% identical), mouse Rny1 (97% identical), rat Y_RNA (96% identical), rabbit Y_RNA (95% identical). Paralogues in human: Y_RNA (94% identical), Y_RNA (93% identical), Y_RNA (92% identical), RNY1P11 (91% identical), Y_RNA (91% identical), Y_RNA (90% identical), RNY1P8 (89% identical), Y_RNA (89% identical), Y_RNA (88% identical), Y_RNA (87% identical), RNY1P10 (86% identical), RNY1P12 (86% identical), and 101 more.
Diseases named in the same sentence as RNY1 in open-access papers:
RNY1 is named in the same sentence as 31 diseases in open-access papers, as found by Europe PMC text mining. Sharing a sentence is not in itself a finding about the gene and the disease. The quoted sentences say what the papers report.
bladder cancer (5 papers, 2008 to 2025). "Downregulation of the following has also been identified: RNY1, RNY3, RNY4, and RNY5 in prostate (tissue) and bladder cancer (tissue) and RNY1 (blood serum) in head and neck squamous cell carcinoma." (PMID 40002172, 2025). "These Y RNAs (RNY1, RNY3, RNY4, and RNY5) are reportedly similarly downregulated in human bladder cancer versus normal urothelial bladder tissue and act as a prognostic indicator for this condition." (PMID 37835660, 2023). "siRNA mediated knock-down of RNY1 and RNY3 reduced the number proportion of S phase cells in the HeLa cells; degradation of RNY3 reduced also the number S-phase cells in EJ30 bladder cancer cells." (PMID 29126388, 2017). "Overall, the downregulated hypoxia-related Y RNA expression trend in COM is consistent with the expression level of Y RNAs (RNY1, RNY3, RNY4, RNY5) in human melanoma, prostate, and urinary bladder cancer, and appears to distinguish the metastatic and non-metastatic melanoma." (PMID 38288969, 2024).
lymph node metastases (2 papers, 2017 to 2022). "Presence of lymph node metastases was also associated with decreased RNY1 (p < 0.001), RNY3 (p < 0.001) and RNY4 (p = 0.007) expression." (PMID 29126388, 2017). "RNY1, RNY3 and RNY4 expression was associated with advanced stage (muscle invasive BCA, lymph node metastasis) and grade (G3 tumors when opposed to G1 and G2)." (PMID 29126388, 2017). "A low expression of RNY1, RNY3 and RNY4 was associated with muscle-invasive BCA, lymph node metastases and advanced grade." (PMID 29126388, 2017).
autoimmune disease (1 paper, 2024). A disorder resulting from loss of function or tissue destruction of an organ or multiple organs, arising from humoral or cellular immune responses of the individual to their own tissue constituents. "The human genome has four functional Y-RNAs (RNY1, 2, 3, and 5), which are a class of small noncoding RNAs that bind and regulate Ro60, a protein involved in the cell’s response to stress and one identified as an autoantigen in autoimmune diseases." (PMID 38308367, 2024).
Autoimmunity (1 paper, 2026). The occurrence of an immune reaction against the organism's own cells or tissues. "As RNY1 assists Ro60 in its function, depletion of RNY1 might attenuate the protective effect of Ro60 and be an indication of autoimmunity." (PMID 41595515, 2026).
benign prostate hyperplasia (1 paper, 2023). "Oncologists focusing on the human prostate have found that RNY1, RNY3, RNY4, and RNY5 are downregulated in prostate adenocarcinoma versus normal tissue and benign prostate hyperplasia." (PMID 37835660, 2023).
breast cancer (1 paper, 2024). A primary or metastatic malignant neoplasm involving the breast. "Another type of tsRNAs, called sex hormone-dependent tRNA-derived RNAs (SHOT-RNAs), are produced by sex hormone-induced angiogenin (ANG, known as RNY1 in yeast) cleavage of fully acylated mature tRNAs and are abundantly expressed in breast cancer (BC) and prostate cancer (PC)." (PMID 37692525, 2024).
Sjögren’s syndrome (1 paper, 2026). "RNY1 is a regulator of the protein Ro60, which is a common autoantigen in both SLE and Sjögren’s syndrome." (PMID 41595515, 2026).
urothelial carcinoma (1 paper, 2017). A malignant neoplasm derived from the transitional epithelium of the urinary tract (urinary bladder, ureter, urethra, or renal pelvis). "The expression of all four YRNAs (RNY1, RNY3, RNY4, RNY5) was determined in archival BCA (urothelial carcinoma, n = 88) and normal urothelial bladder (n = 30) tissues using quantitative real-time PCR." (PMID 29126388, 2017).
cancer (8 papers, 2008 to 2024). A tumor composed of atypical neoplastic, often pleomorphic cells that invade other tissues. "YRNAs are overexpressed in various cancer cells, and RNY1 and RNY3 inhibition was shown to decrease cell proliferation." (PMID 29126388, 2017). "Expression of YRNA was significantly correlated with BCA patients’ overall (RNY1, RNY3, RNY4) and cancer-specific (RNY1, RNY3) survival (all log rank p < 0.05)." (PMID 29126388, 2017). "The distribution of ATAC-seq values for of human vtRNA3-1P, vtRNA2-2P and RNYs (RNY1, RNY3, RNY4 and RNY5) in Pan-Cancer TCGA dataset (385 tumors samples across 23 cancer types) expressed as log2 normalized values." (PMID 34354812, 2021). "C. ATAC-seq values for of human vtRNA3-1P, vtRNA2-2P and RNYs (RNY1, RNY3, RNY4 and RNY5) in 21 different tumors with at least 5 tumor samples available in Pan-Cancer TCGA dataset (385 tumors samples) expressed as log2 normalized values." (PMID 34354812, 2021). "We also performed univariate and multivariate Cox regression analyses: RNY1 and RNY3 were significantly predictive for cancer-specific and overall survival (all p < 0.05), but lost their predictive value in a multivariate model." (PMID 29126388, 2017). "Furthermore, expression of RNY1 and RNY3 was predictive for BCA patients’ overall (also RNY4) and cancer-specific survival as estimated using Kaplan-Meier and univariate (but not multivariate) Cox regression analyses." (PMID 29126388, 2017). "Importantly, the expression levels of RNY1 and RNY3 were significantly predictive for cancer-specific and overall survival of BCA patients with a clear trend for RNY4." (PMID 29126388, 2017). "As the here identified candidates VTRNA1-1, RNY1, and RNY4 have been suggested to distinguish cancer from normal counterparts, and VTRNA1-1 also to inhibit apoptosis and affect chemoresistance, they could have roles in the mechanisms that are involved also in the aggressiveness of TNBC." (PMID 36585466, 2022).
tumor (4 papers, 2008 to 2018). "RNY1, RNY3 and RNY4 show good discriminative ability between tumor and normal tissue, as well as between muscle-invasive and non-muscle-invasive urothelial carcinoma." (PMID 29126388, 2017). "In our study we were able for the first time to show that RNY1, RNY3 and RNY4 could very good discriminate between the normal and tumor tissue with a maximal AUC of 0.863 (RNY3), and to a lesser extent between muscle-invasive and not-muscle-invasive tumors (maximal AUC 0.780 for RNY3)." (PMID 29126388, 2017).
inflammation (1 paper, 2025). Aberrant reaction of the microcirculation characterized by movement of fluid and leukocytes from the blood into extravascular tissues. "Our work demonstrates that levels of RNY1 increase ~8 fold during allergen-induced airway inflammation." (PMID 41427290, 2025).
RNY1 also shares sentences with these, for which no sentence is quoted: cervical carcinoma (2 papers); colon cancer (2); adenocarcinoma (1); Allergy (1); atherosclerosis (1); clear cell renal cell carcinoma (1); glioma (1); head and neck squamous cell carcinoma (1); iron deficiency (1); kidney cancer (1); kidney tumours (1); lung carcinoma (1); melanoma (1); pancreas tumors (1); pancreatic ductal adenocarcinoma (1); prostate adenocarcinoma (1); prostate carcinoma (1); prostate tumours (1); skin aging (1); tuberculosis (1).